PML (PML nuclear body scaffold)
Diseases named in the same sentence as PML in open-access papers (continued):
Sharing a sentence is not in itself a finding about the gene and the disease.
glioma (continued). "SUMOylation of promyelocytic leukemia (PML) protein promoted by prolyl-isomerase Pin1 facilitates c-Myc proteins stability, promoting glioma stem cells (GSCs) maintenance and GBM malignancy." (PMID 37415251, 2023). "The significance of USP11 in glioma tumorigenesis has been demonstrated by its positive regulation on PML, which is downregulated in majority of cancers and played inhibiting cancer role." (PMID 35715413, 2022). "Analysis of glioma clinical biopsies confirmed a positive correlation between SOX9/STAT3/PML and poor patient survival among the cases with the highest SOX9 expression levels." (PMID 35562901, 2022). "We analyzed SOX9, STAT3/p-STAT3, and PML expression in a set of established glioma cell lines and patient-derived cells cultures by immunoblot." (PMID 35562901, 2022). "Further, to study the PML-driven glioma growth and invasive properties, we employed DZNeP, an EZH2 methyl-transferase inhibitor." (PMID 34208139, 2021). "The invasive capacity of the established U87MG glioma cells modified to overexpress the PML protein was investigated." (PMID 34208139, 2021). "The report described solid evidence that after the treatment of TMZ (temozolomide)-resistant glioma cells with both interferon-β (IFN-β) and TMZ, the expression of the endogenous PML gene and its associated protein increased." (PMID 23459691, 2013). "The authors showed that the level of PML protein in human glioma tissue decreased as the degree of malignancy increased." (PMID 23459691, 2013). "Additionally, Pin1 facilitates the sumoylation of PML by SUMO1 in glioma stem cells, which enables PML to interact with and stabilize c-Myc, thereby permitting the survival and carcinogenic potential of glioma stem cells." (PMID 38727267, 2024). "Combined, these results demonstrate that disruption of the PML pathway is an oncogenic driver in pediatric gliomas and could potentially be targeted for therapy." (PMID 38066546, 2023). "Together these studies demonstrated that SOX2 downregulates PML and Sp100 in gliomas." (PMID 37058447, 2023). "We explored the impact of pharmacological inhibition of PML using ATO in glioma cells." (PMID 35562901, 2022). "However, some cases showed an inverse correlation between PML levels and glioma proliferation markers." (PMID 34208139, 2021). "NOTCH signaling could also promote a malignant phenotype in human glioma cell lines and xenograft models by repressing the expression of the promyelocytic leukemia protein (PML) tumor suppressor and inducing the oncogenic long non-coding RNA TUG1." (PMID 33076453, 2020). "In addition, downregulation of PML and Sp100 was observed in glioma samples." (PMID 37058447, 2023). "Analysis of Cancer Cell Line Encyclopedia (CCLE) mRNA expression data confirmed that PML levels are highest in RCC, followed by head and neck squamous carcinoma (HNSC) and glioma." (PMID 38730056, 2024). "Our studies demonstrated that SOX2 downregulated promyelocytic leukemia (PML) and Sp100 and consequently facilitated viral gene expression by decreasing the amount of PML nuclear bodies in HCMV-infected glioma cells." (PMID 37058447, 2023). "This assay showed that SOX2-OE inhibited the promoter activity of PML but not Sp100 in 293T and glioma cells." (PMID 37058447, 2023). "We found that PML-NB dots in SOX2-OE cells were much fewer in number and smaller in size than those in Ctl cells, arguing that SOX2-induced downregulation of PML and Sp100 disrupts PML-NBs formation in glioma cells." (PMID 37058447, 2023). "In glioma, treatment with therapeutic kinase inhibitor against PI3K, AKT or mTOR increased PML protein levels, which may contribute to drug resistance." (PMID 29416846, 2018). "However, we did not observe significant changes in PML and Sp100 expression in HCMV-infected glioma cells." (PMID 37058447, 2023).
acute leukemia (15 papers, 2012 to 2025). A clonal (malignant) hematopoietic disorder with an acute onset, affecting the bone marrow and the peripheral blood. "BCL-2 functions in cooperation with PML-RARA fusion protein to promote acute leukemia and prevent neutrophil differentiation." (PMID 40386562, 2025). "Building on the work above, we analyzed another DNA-FISH dataset from a patient with PML-RARA acute leukemia before and after treatment with all-trans retinoic acid." (PMID 40890868, 2025). "APL with PML::RARA fusion gene and AML with NPM1 mutation represent 2 distinct acute leukemias characterized by recurrent genetic abnormalities." (PMID 39432585, 2024). "The survivin mRNA expression positive rate in de novo and relapse groups, and PML/RARα fusion gene L-type positive groups, was obviously higher than those in remission period groups and was significantly lower than those in acute leukemia groups." (PMID 22550469, 2012). "However, bone marrow aspirates testing for acute leukemia fusion genes by qPCR revealed the presence of the PML::RARA fusion." (PMID 39911670, 2024). "For this reason, the definition of APL with PML‐RARA has been included in “the 2016 revision of the World Health Organization classification of myeloid neoplasms and acute leukemia,” in order to stress the prominent role of the PML‐RARA rearrangement to define this AML subtype." (PMID 34042280, 2021). "In the next step, we sought to identify f-circRNAs based on actual BioProject RNA-Seq data at the example of H3122 cells, an NSCLC cell line harbouring the EML4-ALK fusion (BioProject ID PRJNA350335) and of various acute leukemia samples with PML-RARα fusion gene (BioProject ID PRJNA315254)." (PMID 32470133, 2020). "The survivin mRNA expression positive rate in the de novo and relapse groups, and PML/RARα fusion gene L-type positive groups was obviously higher than those in remission period groups (P < 0.05) and was obviously lower than those in acute leukemia grougs (P < 0.05, <0.001)." (PMID 22550469, 2012). "APL is characterized by the production of a fusion transcript of promyelocytic leukemia (PML) and retinoic acid receptor alpha (RARA) genes and is now the most frequently curable acute leukemia in adults." (PMID 39595968, 2024). "PML is targeted by arsenic trioxide (ATO), a drug approved for acute leukemia." (PMID 41026253, 2025). "Hereby, we present a clinical APL case, reported negative by FISH, where PML-RARA fusion was detected by next generation sequencing (NGS) within 48 h, indicating the benefit of incorporating rapid NGS into the routine diagnostic management of acute leukemia patients." (PMID 40783621, 2025).
melanoma (14 papers, 2011 to 2025). A malignant, usually aggressive tumor composed of atypical, neoplastic melanocytes. "The formation of promyelocytic leukemia protein nuclear bodies (PML-NB) is functionally implicated in cellular senescence in melanoma and is commonly used as senescence marker." (PMID 35565278, 2022). "The promyelocytic leukemia protein (PML), a protein implicated in cellular senescence in melanoma, is involved in the development of these SAHF, just like gamma-H2AX." (PMID 33562468, 2021). "When the effect of the SIM mutations on ORF61 association with PML NBs was examined in melanoma cells at 6 h after infection, all three ORF61 SIM mutants formed minute ORF61-positive nuclear puncta, colocalizing with PML NBs." (PMID 21901090, 2011). "DDX43 regulates RAS protein expression and AKT activation, prevents the expression of PML in ABCB5+ malignant melanoma-initiating cells, and plays a critical role in the male sex differentiation of channel catfish (Ictalurus punctatus)." (PMID 41157636, 2025). "The promyelocytic leukemia protein (PML), a protein functionally implicated in cellular senescence in melanoma, is involved in the development of these SAHF." (PMID 32455577, 2020). "Using SSA-SEM we first analyzed a VZV-infected melanoma cell nucleus in which endogenous PML was expressed." (PMID 22685402, 2012). "The samples for tomography consisted of HPF/FS-treated and epoxy resin-embedded VZV infected melanoma cells that expressed PML IV together with endogenous PML." (PMID 22685402, 2012). "We next used SSA-SEM to analyze VZV-infected melanoma cells that express PML IV when induced with doxycycline, together with endogenous PML." (PMID 22685402, 2012). "Since ORF61 is expressed and colocalizes with PML NBs at very early times in VZV-infected cells, we investigated the pattern of ORF61 association with PML NBs in transfected melanoma cells." (PMID 21901090, 2011). "When melanoma cells were transfected with the PML isoforms and infected with VZV, ORF23 protein was redistributed and colocalized with more than 95% (N = 550) of PML-NBs only in cells that expressed PML IV or EGFP-PML IV." (PMID 21304940, 2011). "SiHuR-transfected melanoma cells showed a strong increase in PML accumulation." (PMID 32455577, 2020). "We therefore asked whether the PML IV cages formed in our inducible melanoma cell lines were functionally like PML clastosomes as determined by their capacity to sequester GFP-tagged Htt." (PMID 21304940, 2011). "However, even with IFN treatment, PML NB frequencies in melanoma cells remained significantly lower than frequencies observed in skin cells in vivo." (PMID 21901090, 2011). "We used the GEPIA database to investigate the prognostic analysis of TRIM2, TRIM7, TRIM8, TRIM18 (MID1), TRIM19 (PML), TRIM27, and TRIM29 in melanoma." (PMID 33118318, 2020). "Despite the compromised effect on PML NB dispersal, the growth kinetics of all three ORF61 SIM mutants was similar to pOka in melanoma cells, as determined by infectious focus assay." (PMID 21901090, 2011). "The number of PML-NBs decreased by about five-fold in both HELF and melanoma cells at 48 hr after infection compared to uninfected HELF and melanoma cells." (PMID 21304940, 2011). "However, the roles of CSTB, GBF1, PML and ICAM1 in melanoma development were still unclear, which deserved to further exploration." (PMID 37217516, 2023). "While we could detect a significant increase of nuclear PML staining in NHEM, there was only a tendency toward an upregulation in melanoma cells treated with etoposide." (PMID 35563794, 2022). "Differential expression of TRIM2, TRIM7, TRIM8, TRIM18 (MID1), TRIM19 (PML), TRIM27, and TRIM29 may play an important role in the development of melanoma." (PMID 33118318, 2020). "Typically, 15–20% of malignant melanomas possess NRAS gene mutations, but no cases of NRAS-mutated PML have been reported in the English literature." (PMID 32028967, 2020).
melanoma (continued). "In control cells that were not transfected but were infected with VZV, the ORF23 capsid protein showed no redistribution if endogenous PML-NBs were completely dispersed as happens in the majority of infected melanoma cells." (PMID 21304940, 2011). "Since melanoma cells have fewer PML-NBs than HELF before infection, the majority of infected melanoma cells had no PML-NBs left." (PMID 21304940, 2011). "However, as previously reported, immunoblot analysis with a polyclonal anti-PML antibody showed that PML protein levels were not decreased in infected HELF or melanoma cells." (PMID 21304940, 2011).
gastric cancer (13 papers, 2011 to 2025). A primary or metastatic malignant neoplasm involving the stomach. "Recently EBNA1 was found to induce the loss of PML nuclear bodies in both NPC and gastric carcinoma cells, by promoting the degradation of the PML proteins." (PMID 23170171, 2012). "Based on these results, we propose that loss of PML protein expression in gastric cancer cells contributes to increased IP-10 transcription via enhancement of STAT-1 activity, which, in turn, promotes lymphocyte trafficking within tumor regions." (PMID 22022583, 2011). "In the present study, we offer evidence that loss of expression of the tumor suppressor protein, PML, contributes to enhancement of lymphocyte infiltration into gastric cancer tissue, via regulation of IP-10 expression." (PMID 22022583, 2011). "Importantly, the EBNA1-induced loss of PML appears to hold up in tumours, as EBV-positive gastric carcinoma tumour samples were found to have considerably less PML than their EBV-negative counterparts." (PMID 23170171, 2012). "Recently, overexpression of PML was reported to inhibit cell growth and to significantly increase cell apoptosis in gastric cancer cells." (PMID 34215258, 2021). "Because RUNX1 is essential for the development of human hematopoietic stem cells, we proposed that PML is a potential drug target that can overcome platinum resistance in the platinum-based chemotherapy in gastric cancer." (PMID 26897165, 2016). "EBNA1 was found to induce the loss of PML nuclear bodies in both NPC and gastric carcinoma cells, by inducing the degradation of the PML proteins." (PMID 24278697, 2012). "PML protein expression is reduced or abolished in many different cancers, including prostate, breast, CNS, colon, lung, and gastric cancer." (PMID 22022583, 2011). "The results clearly show that secretion of IP-10 from gastric cancer cells is increased when PML expression is reduced." (PMID 22022583, 2011). "SNU-638 gastric cancer cells expressed high levels of PML protein, consistent with previous findings, whereas SNU-638 cells transfected with Pml siRNA displayed reduced levels of endogenous PML expression (∼46–56%), as confirmed by immunoblotting." (PMID 22022583, 2011). "We examined the function of PML with respect to lymphocyte recruitment using human gastric cancer tissue samples, Pml+/+ and Pml−/− MEFs, and PML knockdown in both NIH3T3 and SNU-638 cells." (PMID 22022583, 2011). "Immunohistochemical staining for PML and CD8 was performed to explore whether the extent of lymphocyte infiltration was associated with PML expression status in advanced gastric cancer." (PMID 22022583, 2011). "Therefore, the loss of PML and PML NB disruption by EBNA1 is one mechanism by which EBV may contribute to the development of gastric cancer." (PMID 23734343, 2013). "Importantly, these observations in cell lines appear to hold true in vivo, as a comparison of EBV-positive and EBV-negative gastric carcinoma tumour biopsies showed that PML levels were greatly reduced by the presence of EBV, presumably due to the action of EBNA1." (PMID 24278697, 2012). "In view of the loss of PML protein expression and the increase in infiltration of CD8+ T-lymphocytes into advanced gastric carcinoma tissues, we hypothesized that PML contributed to T-cell infiltration/migration in gastric cancer." (PMID 22022583, 2011). "PML/RARα is known to enhance STAT3 expression, and STAT3 has been reported to epigenetically silence NR4A3 expression in gastric cancer." (PMID 36040481, 2022).
gastric cancer (continued). "Although EBNA1 was found to induce the degradation of promyelocytic leukemia (PML) nuclear bodies (also called ND10) in both NPC and gastric carcinoma cells, its effect remains unclear in B-lymphoma cells." (PMID 32176739, 2020). "To determine whether the inhibitory effect of PML on IFN-γ-induced IP-10 promoter activity is occurred in gastric cancer cells lines, we performed similar experiments with SNU-638 gastric cancer cells." (PMID 22022583, 2011). "In our system, IP-10 secretion was observed in gastric cancer SNU-638 cells, NIH3T3 fibroblasts, and MEFs, in response to IFN-γ, and secretion was enhanced in the absence of PML protein expression." (PMID 22022583, 2011).
hepatocellular carcinoma (13 papers, 2012 to 2025). A malignant tumor that arises from hepatocytes. "We previously showed that PML knockdown promotes early-onset hepatocellular carcinoma (HCC) in hepatitis B virus surface antigen (HBsAg)-transgenic mice." (PMID 27058621, 2016). "In addition, MYC regulates metabolic functions attributed to PML, including fatty acid β oxidation and its inhibition induces cellular senescence in lymphoma, osteosarcoma, and hepatocellular carcinoma." (PMID 31570853, 2020). "Increased expression of PML was observed in tumor cells of Hodgkin lymphoma and hepatocellular carcinoma suggesting an oncogenic role of PML but its functional significance is unknown." (PMID 24886876, 2014). "In our analysis, higher PML expression in the Short TL group than in the Long TL group was observed in five cancer types (STAD, THYM, hepatocellular carcinoma (LIHC), LGG, and cholangiocarcinoma (CHOL)), suggesting that PML expression level is a marker for telomere length in these cancer types." (PMID 32784588, 2020). "Similarly, PML is known to modulate interleukin (IL)-6-induced STAT3 activation and hepatoma cell growth by interacting with HDAC361." (PMID 30143675, 2018). "In addition to that, we were able to previously show a direct link between PML and TRAIL in HCC cell lines by RNAi silencing of PML, resulting in down-regulation of TRAIL expression in hepatoma cells." (PMID 22984515, 2012).